JAK2 (Janus kinase 2)
Diseases named in the same sentence as JAK2 in open-access papers (continued):
Sharing a sentence is not in itself a finding about the gene and the disease.
leukemia (continued). "Yet, our data show that loss of NFAT1 function does not affect leukemia onset and outcome in T-ALL induced in mice by activated NOTCH1 (ICN1) or activated JAK2 (TEL/ETV6-JAK2), indicating lack of tumor suppressive function of Nfat1 in early T cell progenitors." (PMID 34234374, 2021). "LS104 is a novel non-ATP-competitive Jak2 inhibitor developed for the treatment of leukemia and MPD." (PMID 34680353, 2021). "Considering the crucial role of JAKs in the development and function of hematopoietic cells, it is not surprising that JAK1, JAK2, and JAK3 mutations are often found in leukemia." (PMID 33672930, 2021). "As relapse occurs, blast counts increase, but the initial JAK2 clone does not increase in frequency, as the genetics of the leukemia has clearly changed with treatment." (PMID 31352405, 2019). "In the HEL JAK2V617F cell line, but not in U937 JAK2 wild-type leukemia cell lines, IRS2 was constitutively phosphorylated and associated with JAK2." (PMID 30328953, 2018). "While expression of mutant Jak2 was necessary for leukemia induction, neither its continued expression nor enzymatic activity was required to maintain leukemia survival and rapid proliferation." (PMID 29907650, 2018). "To further support the hypothesis that CM363 was able to inhibit constitutive pYStat5 in leukemia cells, we assessed the effects of CM363 on HEL, a human erythroleukemia cell line harboring constitutive activation of Jak2/Stat5 signaling pathway." (PMID 27557509, 2017). "In addition, we detected the presence of HSP90- HMWNC that contained BCR-ABL, JAK2, and STAT3 in the high molecular weight region in the cell lysate from Imatinib (IM)-resistant 32Dp210 T315I mouse leukemia cells." (PMID 27551334, 2016). "In addition, activating JAK2 gene fusions with the TEL (ETV6) (TEL-JAK2) and PCM1 genes has been identified in leukemia patients." (PMID 27752371, 2016). "Although the evolution of a JAK2-V617F+ MPN to a mixed-lineage leukemia has been reported in the pediatric population, no evolutions into sAML have been described." (PMID 24744787, 2014). "On the other hand, it was reported that BCR-ABL directly phosphorylates STAT5 in BCR-ABL-transduced cells, and that Jak2 is not required for initial myeloid transformation and leukemia maintenance in a Jak2 conditional knockout model." (PMID 25226617, 2014). "Although we did not tried to combine the two drugs at their IC50s in this cell line, we showed that inhibiting JAK2 resulted in reduced STAT5 activity and enhanced imatinib efficacy even when leukemia cells were protected by hematopoietic stromal cells-mediating cytokine/chemokine production." (PMID 24775308, 2014). "To determine whether these dual activities of ganetespib on JAK2/STAT signaling and cell cycle progression observed in vitro translate into antitumor efficacy in vivo, we established an orthotopic leukemia model using HEL92.1.7 cells." (PMID 21533169, 2011). "The combination of JAK2 inhibitors with epigenetic modulators, such as histone deacetylase inhibitors (HDAC inhibitors) or DNA methyltransferase inhibitors (DNMT inhibitors), offers the potential to reverse the epigenetic alterations that contribute to leukemia progression and resistance." (PMID 40486651, 2025). "Irrespective of that, HDACi deplete wild-type JAK2 in leukemia cells." (PMID 40877230, 2025). "By combining JAK2 inhibitors with other targeted therapies, such as inhibitors of BCL-2 (to promote apoptosis) or FLT3 inhibitors (to block additional tyrosine kinase signaling), it is possible to simultaneously target multiple signaling pathways that drive leukemia." (PMID 40486651, 2025). "Given that cis-pQTL did not support a role for SRP14 with leukaemia risk, it is therefore possible that SRP14, as a biomarker of imminent leukaemia diagnosis, may indicate constitutively active JAK2." (PMID 38750076, 2024).
leukemia (continued). "A previous study demonstrated that mutated JAK2 (Janus kinase 2), not dysfunctional RCAN1, may be a common molecular event in leukemia associated with Down syndrome." (PMID 35717152, 2022). "Leonurine down-regulates miR-18a-5p and enhances SOCS5 expression to curb JAK2/STAT3 signaling pathway activation, impeding CML cells’ proliferation, migration, and colony formation, boosting their apoptosis, and thus exerting a prominent anti-leukemia function in chronic myeloid leukemia." (PMID 36333771, 2022). "The same study showed that CHZ868 potently suppressed the growth of MHH-CALL4 leukemia cells with IC50 values in the range of 100 nM, while 1 μM of CHZ868 suppressed Jak2 phosphorylation, suggesting the involvement of other signaling pathways than Jak2 in the growth regulation of these cells." (PMID 34680353, 2021). "As has been found for other tyrosine kinase fusion proteins in leukemia, the coiled‐coil motifs derived from RNPC3 likely contribute to the dimerization or oligomerization of RNPC3‐JAK2 chimera, with consequent constitutive activation of the JAK2 kinase domain." (PMID 31885183, 2020). "To further support the hypothesis that NPQ-C6 was able to inhibit constitutive pYSTAT5 in leukemia cells, we investigated the effects of NPQ-C6 on HEL, a human erythroleukemia cell line in which the JAK2/STAT5/STAT3 signaling pathway is constitutively activated due a JAK2 mutation (V617F)." (PMID 30687103, 2018). "Similarly, knockdown of Jak2 in Eμ-Crlf2/Jak2P933R B-ALLs also resulted in enhanced survival of recipient mice, although not to the same extent as seen using Eμ-Crlf2/Jak2R683G leukemias." (PMID 29907650, 2018). "In vivo Jak2 depletion in mice bearing Eμ-Crlf2/Jak2R683G leukemias using two different shRNAs resulted in significantly reduced peripheral WBC count, reduced leukemic burden in the spleen, and a marked survival benefit that correlated with knockdown efficiency of the Jak2 shRNAs." (PMID 29907650, 2018). "Native JAK2 in normal cells is phosphorylated by oligomerization of growth factor or cytokine receptors, whereas ligand-independent oligomerization of receptor and non-receptor TK in leukemias and solid tumors have been reported." (PMID 22384256, 2012). "However, targeting JAK2 in isolation may not be sufficient to overcome the complex interplay between leukemia cells and their surrounding environment." (PMID 40486651, 2025). "Thus, targeting JAK2 may not be universally effective across all pediatric leukemia cases, and treatments must be tailored to the specific genetic profile of the leukemia." (PMID 40486651, 2025). "JAK2 mutated clones were also described to show irregular growth trajectories and JAK2 activation to contribute to PD-L1 expression, which may explain the response of JAK2 MRCH to graft-versus-leukemia effects and their relevance after HSCT without mac conditionings." (PMID 37880479, 2024). "While type II JAK2 inhibitors are not currently in clinical development, other strategies aimed at complete inhibition of JAK2 (such as HSP90 inhibitors) may produce greater anti-leukemia efficacy than ruxolitinib in CRLF2-re Ph-like ALL." (PMID 29487712, 2018). "Recent works revealed that STAT5 overexpression leads to a TKI-resistant phenotype, an effect that is independent of JAK2 expression, and that targeting STAT5 by drugs, like the neuroleptic drug pimozide might be a promising perspective in the pharmacology of leukemia and other cancers as well." (PMID 29100302, 2017).
gastric cancer (157 papers, 2004 to 2025). A primary or metastatic malignant neoplasm involving the stomach. "Another patient with PV and JAK2 V617F variant has β-thalassemia minor with a strong family history of β-thalassemia, gastric cancer, and lymphoma." (PMID 40047910, 2025). "Considering the JAK2 polymorphism rs2230724, the increased risk of gastric cancer associated with the rare genotypes was significant in subjects ages >56 years (P = 0.002, adjusted OR = 2.25, 95% CI = 1.36–3.71), but not in subjects ages ≤56 years." (PMID 23717640, 2013). "In this work, a hospital-based case-control study was conducted to examine the association between the JAK2 polymorphisms and the risk of development or progression of gastric cancer in a Chinese Han population." (PMID 23717640, 2013). "In our current hospital-based case–control study, we detected the effect of JAK2 rs2230724 and rs1887427 gene polymorphisms on gastric cancer." (PMID 23717640, 2013). "Considering the JAK2 polymorphism rs1887427, individuals with G allele had a 68% increased risk of gastric cancer (P = 0.001, adjusted OR = 1.68, 95% CI = 1.24–2.26)." (PMID 23717640, 2013). "Associations between variant JAK2 genotypes and clinicopathologic characteristics of gastric cancer." (PMID 23717640, 2013). "We also analyzed the associations between the JAK2 rare genotypes and clinicopathologic features of gastric cancer patients in our study." (PMID 23717640, 2013). "The JAK2 gene rs2230724 and rs1887427 polymorphisms are associated with an increased risk of gastric cancer in a Chinese Han population." (PMID 23717640, 2013). "According to our data, we for the first time found that the functional JAK2 polymorphisms conferred an increased risk of gastric cancer in a Chinese Han population." (PMID 23717640, 2013). "In conclusion, our study for the first time demonstrates that the JAK2 gene rs2230724 and rs1887427 polymorphisms are associated with an increased risk of gastric cancer in the Chinese Han population." (PMID 23717640, 2013). "Besides, ROS-modulated JAK2 pathway was reported to be associated with gastric cancer progression and apoptosis." (PMID 31438997, 2019). "Simultaneously, we studied whether JAK2 could counteract the inhibition effect of gastric cancer cells migration and invasion caused by miR-375." (PMID 25055044, 2014). "Given the importance and the potential biological mechanism of rs2230724 and rs1887427, we propose that the JAK2 polymorphisms may be contribute to the differences in susceptibility and severity of gastric cancer." (PMID 23717640, 2013). "Our data suggest that JAK2 polymorphisms may play an important role in men with gastric cancer." (PMID 23717640, 2013). "For example, they demonstrated that CAFs enhance the migration and EMT of gastric cancer cells by activating the Janus kinase 2/signal transducer and activator of transcription (JAK2/STAT3) pathway in gastric cancer cells by secreting IL-6." (PMID 40485724, 2025). "Vortioxetine inhibited gastric cancer cell growth by reducing the kinase activity of JAK2 and Src, but other data, while confirming growth inhibition, indicated that the inhibition of gastric cancer cell growth by vortioxetine involved PI3K/AKT." (PMID 40649933, 2025). "Such protumorigenic effects have been documented in gastric cancer, where B7-H3 modulated the Jak2/STAT3 signaling pathway." (PMID 40214484, 2025). "STAM2 knockdown has been reported to inhibit proliferation, migration, and invasion by affecting the JAK2/STAT3 signaling pathway in gastric cancer." (PMID 39060946, 2024). "Silencing this lncRNA increased the levels of DC-SIGN in gastric cancer cells and increased the activity of the JAK2/STAT3 signaling cascade." (PMID 39309860, 2024).
gastric cancer (continued). "In Helicobacter pylori infection, inhibition of the JAK2/STAT3 pathway reduces the development of gastric cancer." (PMID 39255287, 2024). "It is overexpressed in gastric cancer cells and influences the proliferation, migration, invasion and adhesion of gastric cancer cells by regulating the JAK2/STAT3 signaling pathway accelerating the progression of gastric cancer." (PMID 37505298, 2024). "Xiongyan Wu and colleagues concluded that cancer-associated fibroblasts (CAFs) isolated from gastric cancer can activate the JAK2/STAT3 pathway in gastric cancer cells by secreting IL-6." (PMID 39309860, 2024). "The activation of the IL6/JAK2/STAT3 signaling cascade by SPI1 promotes gastric cancer malignancy and proliferation." (PMID 39309860, 2024). "TANs secrete IL-17a, enhancing the migration, invasion, and EMT of gastric cancer cells, while activating the JAK2/STAT3 signaling pathway in these cells." (PMID 39676857, 2024). "Studies have shown that SIRT6 inhibits the growth of gastric cancer by suppressing the JAK2/signal transducer and activator of the transcription-3 pathway." (PMID 38548549, 2024). "IL-6 secreted by CAFs has been reported to promote epithelial-mesenchymal transition and metastasis of gastric cancer via the JAK2/STAT3 signaling pathway." (PMID 38510850, 2024). "Studies have shown that asiatic acid derivatives can inhibit gastric cancer cell proliferation and invasion by suppressing JAK2 and STAT3 activation." (PMID 37375849, 2023). "miR-375 overexpression suppresses PD-L1 expression in gastric cancer via the JAK2/STAT3 signaling pathway." (PMID 37813900, 2023). "It has been noticed that tumor‐linked neutrophils can produce IL‐17A, promoting epithelial‐mesenchymal transition (EMT) in gastric cancer via JAK2/STAT3 signaling cascade." (PMID 36480232, 2023). "IL-17a secretion by CAFs markedly enhances tumorigenic effects of gastric cancer through the JAK2/STAT3 pathway in the gastric cancer cells in vitro, with CAFs acting as an independent risk factor for DFS and DSS." (PMID 37046676, 2023). "IL-6 can regulate M2-type macrophage polarization by activating the JAK2/STAT3 signaling in gastric cancer cells." (PMID 37679346, 2023). "Another study demonstrated that TQ treatment inhibited the phosphorylation of STAT3 in HGC27, SGC7901, and BGC823 gastric cancer cells, and inhibited the phosphorylation of JAK2 in HGC27 cells." (PMID 36145344, 2022). "It has been shown to induce autophagy and apoptosis in gastric cancer cells by activating mitochondrial ROS accumulation and silencing the JAK2/STAT3 pathway." (PMID 35559037, 2022). "Our findings are consistent with what has previously been reported: that TQ suppressed STAT3 phosphorylation at Tyr705 due to the inhibition of JAK2 activity in gastric cancer." (PMID 35337104, 2022). "Inhibition of JAK2 signaling pathway suppressed the proliferation of gastric cancer in vitro and in vivo." (PMID 35207737, 2022). "EBV-positive gastric cancers are reported to have recurrent mutations of PIK3CA, ARID1A, and BCOR and amplifications of JAK2, PD-L1, and PD-L224." (PMID 34873204, 2021). "SIRT6 overexpression also induced apoptosis of gastric cancer cells via regulating JAK2/STAT3 signaling." (PMID 34927546, 2021). "TQ has also been shown in studies to reduce cell proliferation by blocking the activation of the JAK2/STAT3 signaling pathway in gastric cancer cells both in vitro (HGC27, BGC823, and SGC7901 cell lines) and in a xenograft tumor mouse model." (PMID 35010954, 2021). "TQ inhibited STAT3 phosphorylation at Tyr705 due to JAK2 and Src activity suppression in gastric cancer cell line (HGC27) investigations." (PMID 35010954, 2021). "Recent studies have shown that HCC and gastric cancer-derived GM-CSF bind neutrophil receptors and stimulate JAK2 and STAT3 phosphorylation that promotes expression of PD-L1 on the neutrophil surface, which binds and inhibits PD-1 on cytotoxic T cells." (PMID 33406733, 2021).
gastric cancer (continued). "CYT997 induces autophagy and apoptosis in gastric cancer by triggering mitochondrial ROS accumulation to silence JAK2/STAT3 pathway." (PMID 32576206, 2020). "miR-216a plays a role in the inhibition of gastric cancer metastasis via targeting JAK2/STAT3-mediated EMT, thereby suggesting its role in tumor suppression and, ultimately, gastric cancer development." (PMID 32992741, 2020). "In this study, we reported for the first time that the polarization and generation of pro-tumor M2-like macrophages was strikingly triggered by GC-MSCs in gastric cancer through activation of the JAK2/STAT3 signaling pathway via high secretion of IL-6/IL-8." (PMID 31801938, 2019). "In gastric cancer, miR-375 is markedly downregulated and inhibits cell proliferation by targeting JAK2." (PMID 30744636, 2019). "In gastric cancer, miR-216a restrained tumor cells migration and invasion possibly by targeting JAK2/STAT3-mediated epithelial-mesenchymal transition (EMT)." (PMID 31798627, 2019). "It suppressed the JAK2/STAT3 pathway of gastric cancer cells in vitro and inhibited tumor growth in a xenograft model of gastric cancer in vivo." (PMID 31100782, 2019). "Taken together, these results implicate Genipin in the induction of apoptotic cell death via JAK2/Stat3-regulated Mcl-1 suppression, suggesting that Genipin can potentially be an effective therapy for treating gastric cancer." (PMID 31351462, 2019). "In the present study, we highlight the unique ability of stromal GC-MSCs to induce the polarization of macrophages into a pro-tumor M2 subtype within the gastric cancer niche through the secretion of IL-6 and IL-8 via the JAK2/STAT3 signaling pathway." (PMID 31801938, 2019). "Several other drugs or compounds can also effectively dephosphorylate JAK2/STAT3 by inducing SHP-1 expression in gastric cancer, including multiple kinase and other natural compounds." (PMID 30202514, 2018). "Previous studies have demonstrated that miR-375 inhibits cell proliferation of gastric cancer cells by repressing JAK2, ERBB2, and YWHAZ18,46–48." (PMID 30258124, 2018). "ATO effectively inhibits cellular invasion, EMT, and tumorigenesis in gastric cancer cells which are mediated by dephosphorylation of JAK2/STAT3 through increase of SHP-1 expression." (PMID 29409467, 2018). "shRNA-mediated B7-H3 silencing in the N87 gastric cancer cell line suppressed cell migration and invasion in vitro and in vivo; downregulated metastasis-associated CXCR4; and inhibited AKT, ERK, and Jak2/Stat3 phosphorylation." (PMID 29069741, 2017). "Researchers also showed that CAFs induced EMT in gastric cancer cells via secreting IL-6 that activated JAK2/STAT3 signaling pathway." (PMID 29383119, 2017). "The authors identified distinct mutations and epigenetic profiles (recurrent PIK3CA mutations, high DNA hypermethylation levels and amplification of JAK2, CD274 and PDCD1LG2) in EBV-associated gastric cancer cases." (PMID 28454117, 2017). "Previous study has reported that gastrin acting on CCK-BR induces cyclooxygenase-2 expression through JAK2/STAT3/PI3K/Akt pathway in human gastric cancer cells." (PMID 27518872, 2016). "Studies in gastric cancer and in lymphomas have described a recurring 9p24.1 amplicon that includes PD-L1, PD-L2, and JAK2." (PMID 26317899, 2015). "In this study we demonstrate that WP1066 dose-dependently inhibits the JAK2/STAT3 signaling pathway in human gastric cancer (AGS) cells, with a consequent 60% reduction in cell proliferation, and a smaller increase in apoptosis." (PMID 24804649, 2014). "Overexpression of miR-375 reduced gastric cancer cells migration and invasion activities at least partially by targeting JAK2." (PMID 25055044, 2014).